MMP9 (matrix metallopeptidase 9)
Diseases named in the same sentence as MMP9 in open-access papers (continued):
Sharing a sentence is not in itself a finding about the gene and the disease.
endometriosis (104 papers, 2006 to 2026). The growth of functional endometrial tissue in anatomic sites outside the uterine body. "The aim of this study was to systematically assess the serum expression of MMP-9 in the existing literature on endometriosis patients and to investigate its association with disease severity, clinical symptoms, and other influencing factors." (PMID 39544239, 2024). "Nevertheless, findings from studies on the serological concentrations of MMP-9 in endometriosis and its diagnostic significance have been conflicting." (PMID 39544239, 2024). "This study systematically evaluated the potential efficacy of serum matrix metalloproteinase-9 (MMP-9) concentration as a diagnostic marker for endometriosis through meta-analysis." (PMID 39544239, 2024). "Tissue remodeling is promoted by MMP-2 and MMP-9, which play a role in the generation of adhesions, the fibrous tissue that can cause tissues to adhere together in endometriosis." (PMID 38398530, 2024). "Expression of MMP-9 in >80% of endometrial cells was associated with a higher risk for endometriosis (OR 4.44 95% CI 1.31 to 15.56) compared to MMP-9 expression in 50%–80% of cells." (PMID 32498419, 2020). "The pathogenic role of MMP-9 has also been demonstrated in endometrial epithelial cells of patients with endometriosis." (PMID 30981279, 2019). "In contrast, we have shown, for the first time, a significant association between the expression of MMP-9 and altered an PR-A/PR-B ratio in endometrium (eutopic) tissues of women with endometriosis compared to a normal control group." (PMID 31037923, 2019). "This study shows that Rg3E significantly downregulates MMP2 and MMP9, blocking a significant pathogenic pathway of endometriosis." (PMID 29247225, 2017). "MMP9 encodes for a metalloproteinase that has a purported role in the progression of invasion in endometriosis as well as angiogenesis and fibrosis, has involvement in a variety of inflammatory autoimmune diseases, and has been suggested to be a therapeutic target for autoimmune conditions." (PMID 40262193, 2025). "The results of the meta-analysis suggest that elevated serum levels of MMP-9 in patients with endometriosis may serve as a potential diagnostic marker, but more high-quality studies are needed to confirm these effects." (PMID 39544239, 2024). "Articles investigating the association between MMP-9 and endometriosis, published from the inception of the databases until February 2024, were systematically retrieved from multiple databases, including PubMed, Embase, Cochrane, Web of Science, Scopus, and CNKI." (PMID 39544239, 2024). "Hence, this study aimed to comprehensively analyze the data from multiple studies to assess the diagnostic value of serum MMP-9 concentration for endometriosis." (PMID 39544239, 2024). "Hence, conducting a meta-analysis to comprehensively evaluate existing studies is crucial for clarifying the reliability and accuracy of MMP-9 as a serological diagnostic marker for endometriosis." (PMID 39544239, 2024). "We hypothesize that TNF-stimulated macrophage production of MMP9 represents one potential mechanism underlying the generation and maintenance of endometriosis." (PMID 39544239, 2024). "Metalloproteinases (MMP-9) and collagenases are implicated in collagen degradation within fetal membranes due to physical/microbial inflammatory circumstances that are highly observed in women with endometriosis at first pregnancy." (PMID 34833476, 2021). "Moreover, it has been reported that dehydrocostus lactone, isolated from Aucklandia lappa, inhibited the expression of MMP2 and MMP9 in endometriosis-associated macrophages (EAMs) and influenced the polarization of macrophages." (PMID 34827737, 2021). "In synthesis, these polymorphisms may be able to alter the structure of MMP-9, giving the women an increased risk of developing endometriosis." (PMID 32046116, 2020).
endometriosis (continued). "Since endometriosis influences endometrium receptivity and MMP-9 responses, we explored whether women with endometriosis are predisposed to change in the activity of MMP-2 in eutopic endometrium." (PMID 27695098, 2016). "Therefore, the results of the meta-analysis presented here may provide an important reference for evaluating the diagnostic utility of MMP-9 in endometriosis in the future." (PMID 39544239, 2024). "According to the eight studies, the underlying mechanisms of animal toxins against endometriosis were as follows: induction of apoptosis, inhibition of angiogenesis, reduction of estrogen level, suppression of matrix metalloproteinase (MMP)-9 expression, and anti-inflammatory effect." (PMID 33673020, 2021). "Another meta-analysis including 15 papers with 996 endometriosis patients and 582 non endometriosis patients reported that the concentration of MMP-9 in patients with endometriosis was markedly elevated compared with that in the control group." (PMID 40810077, 2025). "This study investigated the serum levels of NGAL and MMP-9 in women with endometrioma and unexplained infertility, adding to the growing body of research identifying these markers as key contributors to endometriosis." (PMID 40810077, 2025). "Further, MMP9 demonstrated strong discriminatory potential in the classification of adenomyosis and endometriosis (AUC = 0.93)." (PMID 41272701, 2025). "IL-34 enhances MMP-9 expression in endometriosis, whereas IL-37 modulates MMP9 expression in endometrial cells." (PMID 40565017, 2025). "Deep infiltrative endometriosis is characterized by IDO1/COX-2/MMP-9 axis predominance driving tissue destruction and paradoxical Treg recruitment via CCL17/CCL22." (PMID 41488658, 2025). "We found MMP9 levels to be significantly less in adenomyosis, endometriosis, and co-existent adenomyosis–endometriosis groups as compared to controls." (PMID 41272701, 2025). "Resveratrol reduced MMP-2 and MMP-9 levels in the endometrium and blood of women with endometriosis." (PMID 40508002, 2025). "The SRC-1 isoform/MMP-9/ESR2 axis has been identified as a key driver of endometriosis by inhibiting apoptosis and promoting inflammatory responses within endometriotic lesions." (PMID 41054802, 2025). "A 2013 study indicated that an increase in MMP-9 was related to inadequate oocyte and embryo development in women with endometriosis undergoing IVF." (PMID 40810077, 2025). "Even if the patients had other gynecological pathologies, MMP-9 levels were still higher in the endometriosis group than in the control group." (PMID 40810077, 2025). "MMP-9, especially the MMP-9/NGAL ratio, can be used as a diagnostic and follow-up biomarker in endometriosis." (PMID 40810077, 2025). "In rectocervical endometriosis lesions, increased IDO1 expression is associated with increased COX-2 and MMP-9 expression, promoting enhanced adhesion and invasion of endometrial stromal cells." (PMID 41488658, 2025). "Matrix metalloproteinases (MMPs) activity, including MMP2 and MMP9, is elevated in the ectopic tissue of endometriosis." (PMID 40457415, 2025). "Subsequent research should focus on including larger and more diverse patient cohorts to assess the MMP-9/NGAL ratio throughout various phases of endometriosis." (PMID 40810077, 2025). "The heightened activity of MMP-2 and MMP-9 plays a significant role in several important aspects of endometriosis as well." (PMID 38398530, 2024). "By GSEA pathway enrichment analysis, we found that MMP-9 was significantly enriched in the unsaturated fatty acid pathway and tended to be downregulated in endometriosis." (PMID 39544239, 2024). "A sharp spike in matrix metalloproteinase 9 was observed only in the cell culture from a single extragenital endometriosis patient (SMMP-9 = 8.789 ± 1.927%), while in other patients in that group, no such changes in the MMP-9 expression level were registered." (PMID 38255200, 2024).
endometriosis (continued). "One study has shown an increase in MMP-2 and MMP-9 in the sites of endometriosis compared with the eutopic endometrium." (PMID 38255200, 2024). "MMP-2 and MMP-9 are involved in the invasion and dissemination of endometrial cells, which leads to the occurrence and development of endometriosis." (PMID 38398530, 2024). "This is seen in a study by Swarnakar and Paul where matrix metalloproteinase (MMP)-9 activity increased with the severity of endometriosis, and curcumin was shown to reverse this increase in activity to near control levels." (PMID 38558676, 2024). "The observed reduction of MMP-2 and MMP-9 expression in the endometriotic tissue therefore suggests a positive role of resveratrol in the reduction of endometriosis invasiveness." (PMID 38612425, 2024). "The active forms of matrix metalloproteinase MMP-2 and MMP-9 are particularly important during the early stages of extragenital endometriosis development." (PMID 39768606, 2024). "This is consistent with findings that the MMP-2 and MMP-9 activity is increased in women with the eutopic endometrium compared to endometriosis." (PMID 38255200, 2024). "This aligns with our observation of elevated MMP-9 expression in endometriosis patients, consistent with our findings." (PMID 39544239, 2024). "It was shown that the area of MMP-9 expression in endometrial ectopic tissues has a tendency to increase in all stages of extragenital endometriosis." (PMID 38255200, 2024). "Other studies have shown that resveratrol decreases the gene and protein expression of VEGF and MMP-9 in endometrial stromal cells of patients with endometriosis." (PMID 38673959, 2024). "Active forms of MMP-2 and MMP-9 are particularly important at early stages of extragenital endometriosis development." (PMID 38255200, 2024). "Elevated serum MMP-9 levels correlate with the pathogenesis and clinical presentation of endometriosis, suggesting its potential utility as a serological diagnostic marker." (PMID 39544239, 2024). "The aim of our study was to study KISS1/KISS1R, MMP-2, and MMP-9 gene expression and protein synthesis in endometriosis and compare them with the normal endometrium." (PMID 38255200, 2024). "Therefore, we may presume that KISS1, KISS1R, MMP-2, and MMP-9 can be used for the diagnostic, assessment of the progression of endometriosis and the effectiveness of treatment of this disease in women from 23 to 38 years old without endocrine system pathology and oncology diseases." (PMID 38255200, 2024). "The concentration of MMP-9 in the blood of patients with endometriosis was significantly higher compared to that of the control group (p < 0.0001)." (PMID 39544239, 2024). "In turn, high levels of IL-33 enhanced invasion ability of hOVEN-SCs via ST2/mitogen-activated protein kinase (MAPK)/matrix metalloproteinase MMP-9 signaling pathway, ultimately contributing to ovarian dysfunctions and endometriosis progression." (PMID 39713054, 2024). "MMP-9 is known to have a direct effect on endometriosis sites through the system of cytokines and growth factors, affecting angiogenesis and adhesive processes." (PMID 38255200, 2024). "In endometriosis, the expression of MMP-9 is elevated in the endometrium, enhancing the ability of EnSCs to migrate and implant." (PMID 36994440, 2023). "It has also been shown that VEGF, MMP-2 and MMP-9 are significantly elevated in the serum of patients with endometriosis." (PMID 36386543, 2022). "MiR-126 and MMP9 have been also suggested to play a role in development of endometriosis and MMP9 in particular, seems to be a potential marker of the disease." (PMID 35620197, 2022). "Other studies also showed that the expression levels of MMP2, MMP3, and MMP9 in ectopic endometrium and endometriosis cells were amplified." (PMID 36235740, 2022). "MMP-2 and MMP-9 have been extensively studied in the scope of endometriosis, mainly because they are present at high levels in the peritoneal fluid of patients with endometriosis." (PMID 35164046, 2022).
endometriosis (continued). "Our data showed a higher expression of MMP-2 and MMP-9 genes in endometriosis cells (E-MenSCs) (7.6 and 5.8 fold), as compared with NE-MenSCs." (PMID 35059465, 2022). "In keeping with this, we found that metformin treatment in our study significantly reduced MMP-9 expression accompanied with a decrease in the volume of endometrial implants from rats with endometriosis." (PMID 35273494, 2022). "These three venoms are thought to be effective against endometriosis because they have been reported to induce apoptosis, inhibit angiogenesis, reduce estrogen levels, suppress MMP-9 expression, and exert anti-inflammatory effects in preclinical studies." (PMID 33673020, 2021). "In conclusion, the authors emphasized the need for further research on the effect of resveratrol on MMP-2 and MMP-9 expression in women with endometriosis." (PMID 33919512, 2021). "The high levels of PGs and inflammatory cytokines that exist in endometriosis locally activate MMP-9 and determine the lesions’ invasiveness." (PMID 34833476, 2021). "In both endometriosis and cancer, invasion involves MMP family proteins; for instance, MMP9 participates in both the implantation of ectopic endometrium in endometriosis and the invasion of tumor cells and metastasis in cancer." (PMID 34068967, 2021). "PGE2 also regulated matrix metalloproteinase 9 (MMP-9), an enzyme involved in the elimination of cellular debris, which has a low expression in pMφ of women with endometriosis." (PMID 34639133, 2021). "The present study has evaluated the effect of resveratrol on the expression of vascular endothelial growth factor (VEGF), transforming growth factor-β (TGF-β) and matrix metalloproteinase-9 (MMP-9) as factors related to endometriosis progression." (PMID 33723310, 2021). "MMP2 and MMP9 can be regarded as the most typical downstream biomarkers in the progression of endometriosis." (PMID 34827737, 2021). "In the uterine endometrial tissue of women with endometriosis, Collette and Maheux (2006) showed a heightened expression of MMP-9 through zymography and ELISA, but their samples were taken during the proliferative phase of the menstrual cycle." (PMID 32498419, 2020). "Strong MMP-9 staining was found in 66% of endometriosis cells, compared to 26.3% of endometrial cells in the controls (OR 4.44, 95%CI 1.31–15.26, p < 0.005)." (PMID 32498419, 2020). "The odds ratio of endometriosis is increased by the stronger staining of MMP-9 (OR 4.44, 95% CI 1.31–156)." (PMID 32498419, 2020). "In the current study, we demonstrate that the expression of endometrium MMP-2 and MMP-9 are increased in patients with endometriosis." (PMID 33072202, 2020). "We also examined the possible correlation between MMP-2 and MMP-9 levels in eutopic and ectopic endometrium in patients with endometriosis." (PMID 33072202, 2020). "Of the various types of proteins found in endometriosis cells, MMP-9 and TIMP-1 were detected in peritoneal fluid and menstrual blood." (PMID 32498419, 2020). "While there is still a need to further elucidate the interaction between these factors, our findings support an increased expression of MMP-9 in endometriosis." (PMID 32498419, 2020). "Matrix metalloproteinase (MMP9) expression increased in the endometrium from women with endometriosis." (PMID 32334621, 2020). "In fact, the levels of MMP-2 and MMP-9 were found to be higher in the peritoneal fluid of women with endometriosis compared to that of healthy patients." (PMID 33121166, 2020). "A panel composed of MMP-2, MMP-9, and MMP-9/neutrophil gelatinase-associated lipocalin was found to increase in 33 subjects with confirmed endometriosis when compared to controls." (PMID 32143439, 2020). "Increased matrix metalloproteinase-9 (MMP-9) co-localized with CD68+ macrophages in the endometrium of women with endometriosis is indicative of an increase in the number of macrophages implicated in tissue remodeling." (PMID 32038499, 2020).
endometriosis (continued). "Proteolytic enzymes, like gelatinases (MMP-2 and MMP-9), play an important role in the initial development of endometriosis through ECM degradation." (PMID 31037923, 2019). "Both overexpression and elevated activity of MMP-9 in endometriosis are believed to be regulated by nuclear factor kappa-B (NF-кB)." (PMID 31037923, 2019). "Matrix metalloproteinases (MMPs), especially the gelatinases MMP-2 and MMP-9, play a crucial role in the pathogenesis of endometriosis by enabling invasion." (PMID 30981279, 2019). "This hypothesis may be correlated further by our observations since overexpression of MMP-9, as a consequence of an imbalanced PR-A/PR-B ratio in endometriosis, may affect the function of the follicular microenvironment, as well as oocyte and embryo quality, which cause infertility in endometriosis." (PMID 31037923, 2019). "Firstly, by enzyme linked immunoabsorbent assay, we found that IL-34, VEGF, MMP-2 and MMP-9 were increased in the sera of patients with endometriosis." (PMID 31727934, 2019). "There is increased expression of MMP-9 in endometrium and in peritoneal fluid in endometriosis, and MMP-9 cleaves CXCL9 at three different sites and degrades CXCL10." (PMID 30621017, 2019). "MMP-2 and MMP-9 levels were shown to be higher in patients with endometriosis than in healthy controls." (PMID 30888523, 2019). "The results showed that VEGF, MMP-2 and MMP-9 were elevated in the sera of the patients suffering from endometriosis." (PMID 31727934, 2019). "We sought to assess the correlation between the expression of MMP-2 and MMP-9 and the PR-A/PR-B ratio in endometriosis." (PMID 31037923, 2019). "It is possible that the increased levels of MMP-9 in endometriosis result in cleavage and degradation of CXCL9 and CXCL10, causing decreased levels of these proteins." (PMID 30621017, 2019). "Our findings are in line with a previous report where STIP1 was shown to stimulate the activity of MMPs; moreover, several studies have indicated that MMP-9 is upregulated in endometriosis." (PMID 29304094, 2018). "MMP-2 and MMP-9 are elevated in the peritoneal fluid of patients with endometriosis compared to healthy people." (PMID 28264481, 2017). "Among the various MMPs, gelatinases MMP-2 and MMP-9, which degrade the principal component of basement membranes, collagen IV, have been intensively investigated in the context of endometriosis." (PMID 28264481, 2017). "We also found elevated MMP-9 activities in the ectopic endometriosis in a stage dependent manner, which corroborated our previous report." (PMID 27695098, 2016). "Studies from our laboratory as well as others have shown that eutopic endometrium of women with endometriosis exhibits higher MMP-9 activities than unaffected women." (PMID 27695098, 2016). "The roles of MMPs in endometriosis are intriguing; there are reports for the presence or elevated expressions of MMP-9, -2, -3 and -7 in human endometriosis." (PMID 27695098, 2016). "For EEECs, the expression of OPN and MMP-9 on cellular surfaces was much higher in stage III/IV than in stage I/II, which suggested that the OPN and MMP-9 expression levels correlated with the severity of endometriosis or the local E2 concentration." (PMID 26289107, 2015). "Several recent studies have examined the increased expression of MMP-9 in patients with endometriosis." (PMID 26289107, 2015). "The expression of MMPs in the eutopic endometrium in endometriosis patients differs from that in normal females, and the expression of the MMP9 protein in the endometrium of endometriosis patients is much higher than that in normal females." (PMID 26432349, 2015). "A panel consisting of MMP-2, MMP-9, and MMP-9/neutrophil gealtinase-associated lipocalin was significantly elevated in a cohort of 33 women with endometriosis relative to expression in a group of 13 controls." (PMID 26240814, 2015).